LMX1B (LIM homeobox transcription factor 1 beta)
Description:
Transcription factor involved in the regulation of podocyte-expressed genes. Essential for the specification of dorsal limb fate at both the zeugopodal and autopodal levels.
Synonyms: FSGS10; LMX1.2; NPS1
Tractability: No criterion of Open Targets' tractability assessment is met for any kind of drug.
Gene: Protein-coding gene on chromosome 9 (126,613,928 to 126,701,032, forward strand). Ensembl gene ENSG00000136944.
Subcellular location: Nucleus
Subcellular location (Human Protein Atlas): Nucleoplasm
Gene Ontology:
Molecular function: DNA-binding transcription factor activity; protein binding; sequence-specific double-stranded DNA binding; DNA-binding transcription factor activity, RNA polymerase II-specific; RNA polymerase II transcription regulatory region sequence-specific DNA binding; DNA binding; sequence-specific DNA binding
Biological process: regulation of DNA-templated transcription; dopaminergic neuron differentiation; dorsal/ventral pattern formation; neuron differentiation; positive regulation of transcription by RNA polymerase II; regulation of transcription by RNA polymerase II
Cellular component: nucleus; chromatin
Genetic constraint (gnomAD): Loss-of-function variants: 10 observed, 41.44 expected, observed/expected ratio (o/e) 0.24, 90% interval 0.15 to 0.41. The upper end of that interval is the gene's LOEUF score, 0.41, which puts it in group 1 of 6, group 1 being the genes least tolerant of losing a copy. Missense variants: 420 observed, 540.46 expected, observed/expected ratio (o/e) 0.78, 90% interval 0.72 to 0.84. Synonymous variants: 227 observed, 222.29 expected, observed/expected ratio (o/e) 1.02, 90% interval 0.92 to 1.14.
Gene-disease validity (ClinGen):
ClinGen rates the evidence that LMX1B causes each of these diseases.
nail-patella syndrome (autosomal dominant): Definitive. A rare hereditary patellar dysostosis characterized by nail hypoplasia or aplasia, aplastic or hypoplastic patellae, elbow dysplasia, and the presence of iliac horns as well as renal and ocular anomalies.
Homologues: Orthologues: chimpanzee LMX1B (100% identical), dog LMX1B (100% identical), pig LMX1B (100% identical), rat Lmx1b (99% identical), macaque LMX1B (98% identical), mouse Lmx1b (98% identical), tropical clawed frog lmx1b (87% identical), guinea pig LMX1B (86% identical), zebrafish lmx1bb (82% identical), zebrafish lmx1ba (76% identical). Paralogues in human: LMX1A (65% identical), ZFHX4 (32% identical), ZFHX3 (30% identical), LHX4 (29% identical), LHX3 (28% identical), LHX1 (27% identical), LHX5 (27% identical), LHX8 (26% identical), LHX6 (25% identical), LHX9 (25% identical), ZFHX2 (25% identical), LHX2 (23% identical), and 8 more.
Diseases named in the same sentence as LMX1B in open-access papers:
LMX1B is named in the same sentence as 80 diseases in open-access papers, as found by Europe PMC text mining. Sharing a sentence is not in itself a finding about the gene and the disease. The quoted sentences say what the papers report.
nail-patella syndrome (53 papers, 2005 to 2026). "Nail-patella syndrome (NPS) is an autosomal dominant disorder caused by the variants of the LMX1B gene, affecting several systems, including musculoskeletal, renal, and ocular systems." (PMID 40421384, 2025). "Other less common diseases include Pierson syndrome which has variants in the laminin β2 (LAMB2) gene and nail-patella syndrome (also known as LMX1B-associated nephropathy) which has mutations in the LMX1B gene." (PMID 41299396, 2025). "Mutations in the human LMX1B gene cause the rare autosomal-dominant disorder Nail-patella syndrome, which affects development of limbs, eyes, brain, and kidneys." (PMID 40829147, 2025). "Although nail-patella syndrome tends to have irregular GBM thickening, there have been cases of nail-patella syndrome with a novel LMX1B variant presented with severe kidney involvement and thin GBM only." (PMID 41299396, 2025). "Nail–patella syndrome (NPS) is a hereditary disease caused by pathogenic variants in LMX1B and characterized by nail, limb, and renal symptoms." (PMID 38424113, 2024). "Away from the midbrain, mutations in the LIM and/or homeodomain of LMX1B cause Nail-Patella syndrome, a human disease characterized by skeletal developmental abnormalities, chronic nephropathy, and open-angle glaucoma." (PMID 37014324, 2023). "Lmx1b is required for the regulation of dorsal-ventral patterning of the limbs and in organ development, including the kidney, brain, and eye, and mutations in Lmx1b were identified in patients with nail patella syndrome (NPS)." (PMID 35563615, 2022). "Studies in humans have also demonstrated the phenotypic variability of glaucoma in patients with Nail-Patella Syndrome, which is caused by mutations in LMX1B." (PMID 34440426, 2021). "Heterozygous mutations in the LIM homeodomain of LMX1B resulted in nail–patella syndrome (NPS), which is characterized by developmental defects of dorsal limb structures and nephropathy." (PMID 32111086, 2020). "A notable CAKUT-causing gene encodes the transcription factor LMX1B, mutations in which can lead to nail-patella syndrome (NPS), a rare cause of autosomal-dominant ESRD." (PMID 30967415, 2019). "Mutations in LMX1B cause Nail Patella syndrome in humans and a third of Nail Patella syndrome patients develop glaucoma, a phenotype also observed in mouse models." (PMID 29916365, 2018). "The patient recently obtained a clinical diagnosis of Nail Patella syndrome, confirmed by the identification of a de novo variant in LMX1B gene." (PMID 30373198, 2018). "LMX1B is mutated in Nail-Patella Syndrome, characterized by nail, patella and elbow dysplasia, in which some patients develop OAG35." (PMID 29449654, 2018). "Mutations in LMX1B are previously established to cause nail-patella syndrome (NPS), a rare developmental disorder characterized by skeletal abnormalities, as well as kidney and eye defects." (PMID 29891935, 2018). "LMX1B is a key regulator of the dorsoventral patterning of limbs, and mutations in LMX1B cause nail patella syndrome." (PMID 29113774, 2017). "In humans, mutations in LMX1B have been linked to nail-patella syndrome, which has been associated with glaucoma." (PMID 27483349, 2016). "It has been reported that LMX1B mutation causes nephropathies and, often, renal failure in human patients affected by Nail-Patella syndrome." (PMID 25098329, 2014). "Nail-patella syndrome is a human genetic disease caused by an inactivating mutation in one copy of a gene called LMX1B, with the amount of protein produced from the remaining copy of the gene not being enough for normal function." (PMID 24809698, 2014). "Mutations in Lmx1b cause nail-patella syndrome (NPS), an autosomal dominant disease with skeletal abnormalities, nail hypoplasia, and nephropathy." (PMID 22693670, 2012).
nail-patella syndrome (continued). "Mutations in LMX1B are dominant due to happloinsufficiency (Nail-Patella syndrome, OMIM 161200;) and the mouse model also shows multiple roles for LMX1B in the development of limb, skeleton, eye, kidney and brain." (PMID 23226461, 2012). "Nail–patella syndrome (NPS) is a pleiotropic autosomal-dominant disorder due to mutations in the gene LMX1B." (PMID 18535845, 2009). "The nail-patella syndrome results from dominant autosomal mutation in the transcription factor LMX1B, which regulates genes COL4A3 and COL4A4 and the children have nephrotic syndrome and skeletal and nail dysplasia." (PMID 16878253, 2005). "Heterozygous loss-of-function variants of LMX1B cause nail-patella syndrome (NPS; MIM: #161,200)." (PMID 40721798, 2025). "Genetic changes in the LIM homeobox transcription factor 1 beta (LMX1B) have been associated with focal segmental glomerulosclerosis (FSGS) without the extra-renal or ultrastructural manifestations of Nail-patella syndrome (NPS) known as Nail-patella-like renal disease (NPLRD)." (PMID 32791958, 2020). "Finally, lmx1b (LIM homeobox Transcription Factor 1 beta) is associated with Nail-Patella syndrome and glaucoma predisposition." (PMID 32528955, 2020). "In spite of the implicated role of lmx1b genes in pathogenic features of the Nail-Patella Syndrome, both lmx1b.1 and lmx1b.2 genes did not display classical AS expression patterns in our WISH assay at early timepoints, 12–48 hpf, but are detected in the AS at later stages, 72 hpf+." (PMID 32528955, 2020). "Mutations in the LIM-homeodomain transcription factor LMX1B cause nail-patella syndrome, an autosomal dominant pleiotrophic human disorder in which nail, patella and elbow dysplasia is associated with other skeletal abnormalities and variably nephropathy and glaucoma." (PMID 24809698, 2014). "Nail-Patella Syndrome (NPS) is an autosomal dominant genetic disease resulting from variants in the homeobox transcription factor LMX1B gene on chromosome 9q34, affecting about 1 in every 50,000 people worldwide." (PMID 40271081, 2025). "Heterozygous mutations in LMX1B cause Nail-patella syndrome (NPS), a rare genetic disorder which predominantly affects the renal and skeletal systems." (PMID 40829147, 2025). "LMX1B mutations can lead to nail-patella syndrome (NPS) or nail-patella-like renal disease (NPLRD) with only renal manifestations." (PMID 38457557, 2024). "In humans, haploinsufficiency of LMX1B causes nail-patella syndrome (NPS) and incomplete limb dorsalization." (PMID 37492222, 2023). "Nail-patella syndrome (NPS) is an autosomal dominant disorder caused by mutations in the LMX1B gene and is characterized by nail dysplasia, skeletal abnormalities, and nephropathy." (PMID 28335748, 2017). "LMX1B mutations, on the other hand, cause dominantly-inherited Nail-Patella Syndrome (NPS; OMIM 161200) in which approximately 33% of patients develop glaucoma." (PMID 22736943, 2012). "LMX1B mutations in humans cause an autosomal dominant inherited disease called nail-patella syndrome (NPS), which is characterized by abnormalities of the arms and legs as well as kidney disease and glaucoma." (PMID 22174793, 2011). "Here, we describe the characterisation of lmx1b stable mutant lines, with a focus on development of tissues that are affected in Nail-patella syndrome." (PMID 40829147, 2025). "Nail–patella syndrome (NPS; OMIM #161200) is an autosomal dominant disorder caused by variants in the LMX1B gene." (PMID 40299366, 2025). "We reported a case of the co-presence of the LMX1B and PAX2 variant in a girl with an extrarenal manifestation of Nail Patella Syndrome but also end-stage renal disease due to congenital bilateral renal hypodysplasia and vesicoureteral reflux." (PMID 36835576, 2023). "LMX1B is the gene responsible for nail–patella syndrome, which involves poorly developed nails and patella and multiple limb malformations, and when knocked out in mice, is associated with abnormal ventral limb development." (PMID 36662418, 2023).
nail-patella syndrome (continued). "Prior to GWAS, dominant mutations in LMX1B were identified to cause nail-patella syndrome (NPS)." (PMID 33462143, 2021). "In humans, LMX1B mutations cause Nail-Patella Syndrome (NPS), an autosomal dominant condition of the nails and patellae, in which around 33% of patients over 40 years old develop open-angle glaucoma (compared to 1–2% of the general population over 40 years old)." (PMID 34440426, 2021). "A genetic test disclosed that the patient was heterozygous for LMX1B, and the diagnosis of nail-patella syndrome was made." (PMID 32774956, 2020). "Heterozygous loss-of-function variants of LMX1B (MIM: 602575), a paralog of LMX1A, have been associated with nail–patella syndrome in human (NPS, MIM: 161200)." (PMID 29754270, 2018). "Interestingly, in humans, just one mutant allele of Lmx1b causes the autosomal dominant disorder nail-patella syndrome (NPS), suggesting that gene dosage is also important in mammals." (PMID 27553035, 2016). "Mouse Lmx1b is expressed in podocytes of the kidney, and its genetic ablation results in kidney defects resembling those observed in Nail-Patella syndrome patients." (PMID 25098329, 2014). "The gene responsible for nail- patella syndrome is located in chromosome 9q34 and is termed as LMX1B." (PMID 22145064, 2011). "Amino acid changes at this particular residue also have been shown to have a disease-causing effect in the case of the homeodomain transcription factors, HLXB9 (Currarino syndrome), LMX1B (Nail-patella syndrome), and PAX3 (Warrensburg syndrome)." (PMID 19052653, 2008). "Nail-patella syndrome (NPS) is an uncommon autosomal dominant condition marked by nail dysplasia, skeletal abnormalities, and variable renal manifestations, resulting from mutations in the LMX1B gene." (PMID 41782702, 2026). "LMX1B mutations linked to nail-patella syndrome (NPS) may also contribute to chronic pain, suggesting heightened pain sensitivity; ATP1A2 helps regulate metabolism by maintaining ion gradients across cell membranes and is linked to pain disorders such as neuropathic pain and fibromyalgia." (PMID 40313396, 2025). "LMX1B haploinsufficiency causes Nail-patella syndrome (NPS; MIM 161200), characterized by nail dysplasia, absent/hypoplastic patellae, chronic kidney disease, and glaucoma." (PMID 34545091, 2021). "Nail-patella syndrome (NPS; OMIM #161200) is an autosomal dominant disease caused by variants in LMX1B which encodes for the LIM homeobox transcription factor 1 beta that plays a critical role in the development of the limb structures, glomerular basement membrane in the eye, kidney, and neurons." (PMID 32791958, 2020). "Nail-patella syndrome (NPS) also known as Fong disease, hereditary onycho-osteodystrophy (HOOD), Österreicher-Turner syndrome, or Turner-Kieser syndrome is a rare autosomal dominant condition, caused by anomalies of the LMX1B gene." (PMID 22574102, 2012). "Overall, these mutant lines demonstrate the utility of zebrafish for modelling Nail-patella syndrome and describe a previously undescribed role for lmx1b in notochord cell inflation." (PMID 40829147, 2025). "Nail-patella syndrome (NPS) is characterized by nail dysplasia, absent/hypoplastic patellae, chronic kidney disease, and glaucoma and can be caused by haploinsufficiency of LMX1B; however, not all patients harbor pathogenic LMX1B mutations." (PMID 34545091, 2021).
glaucoma (31 papers, 2007 to 2026). Increased pressure in the eyeball due to obstruction of the outflow of aqueous humor. "A mutation of the LIM homeobox transcription factor 1-beta (LMX1B) gene in humans was also associated with increased susceptibility to glaucoma." (PMID 38255979, 2024). "This study evaluated the association of the LMX1B locus with baseline optic disc and clinical phenotypic characteristics of glaucoma patients from our African American cohort." (PMID 34440426, 2021). "Identifying genetic modifiers of LMX1B-related phenotypes will be important in understanding the risk of glaucoma and is expected to provide novel mechanistic information on the etiology of IOP elevation." (PMID 33462143, 2021). "Given the phenotypic variation between individuals with the same LMX1B variant, we expected to find differences in glaucoma-associated ocular phenotypes between different genetically diverse mouse strains with the Lmx1bV265D allele." (PMID 33462143, 2021). "Taken together, these associations suggest a possible decreased severity of glaucoma phenotype in African American patients with POAG who have the rs187699205 SNP in the LMX1B gene." (PMID 34440426, 2021). "Mutations in LMX1B are associated with the nail-patella syndrome, in which some patients also develop glaucoma as one of the manifestations of the syndrome." (PMID 34408771, 2021). "LMX1B mutations have been suggested to contribute to glaucoma resulting from ocular developmental anomalies." (PMID 34408771, 2021). "The present study shows that glaucoma phenotypes differ significantly by LMX1B variant in African American patients with POAG." (PMID 34440426, 2021). "In conclusion, glaucoma phenotypes differed significantly by LMX1B variant in African American patients with POAG, and a SNP variant was associated with certain disease features considered lower risk." (PMID 34440426, 2021). "Three suggestive ROSMAP variants at the LMX1B locus were previously reported for association with glaucoma, and replicated in the TCX and FP regions." (PMID 32492070, 2020). "Recently, LMX1B has been reported to be associated with primary open-angle glaucoma, accompanied by development defects of the ocular anterior segments including cornea." (PMID 32193507, 2020). "In this respect, mutations in FOXC1, PITX2, SH3PXD2B and LMX1B, among others, cause various ASDs and have a significantly increased risk of early onset glaucoma." (PMID 27483349, 2016). "Within this interval we considered Lmx1b to be a strong candidate for harbouring the Icst mutation because glaucoma occurs in about 30–40% of NPS patients." (PMID 24809698, 2014). "In this article, we report the ophthalmic, extraophthalmic clinical characteristics and a genetic mutation in LMX1B in a Chilean family having NPS with glaucoma." (PMID 21850167, 2011). "They reported an average age at diagnosis of glaucoma in cases with apparently LMX1B causative mutations of 29.7 years, which is substantially below the expected age at diagnosis for most cases of primary OAG." (PMID 17515884, 2007). "Genetic variants and mutations in LMX1B were previously associated with susceptibility of glaucoma." (PMID 33929592, 2021). "LMX1B has previously been identified as a glaucoma susceptibility locus." (PMID 34440426, 2021). "Further, we identified LMX1B as a glaucoma susceptibility locus." (PMID 29891935, 2018). "Together, these data suggest that mutation of Lmx1b has a primary effect on metabolism in TM3 cells that subsequently leads to IOP elevation and then glaucoma." (PMID 39829808, 2025). "We selected LMX1B because it causes IOP elevation and glaucoma in humans and was identified as a highly active transcription factor in our TM cell dataset." (PMID 39829808, 2025). "Common variants in LMX1B are associated with IOP variation and the most common form of human glaucoma, primary open-angle glaucoma (POAG)." (PMID 40272416, 2025).